NF2 (NF2, moesin-ezrin-radixin like (MERLIN) tumor suppressor)
Diseases named in the same sentence as NF2 in open-access papers (continued):
Sharing a sentence is not in itself a finding about the gene and the disease.
tumor (continued). "Therefore, hormone therapies are not indicated and may even be contraindicated for NF2-related tumours." (PMID 31730023, 2019). "Indeed, it might also be possible to correct the aberrant splicing of NF2/MERLIN reported in MPM tumours that results in in-frame deletions and a non-functioning protein." (PMID 29534050, 2018). "The correlations between the molecular information of the tumor and the data from the microarray study were as follows: NF2 mutated by dHPLC analysis vs. not mutated; NF2 mutated by both dHPLC and MLPA P044 vs. not mutated; 22q LOH present vs. no 22q LOH; 2 or more hits in NF2 vs. 1 or no hits." (PMID 23354516, 2013). "The clinical presentation of this patient was however atypical and distinct from patients with NF2-related SWN as hearing was never lost and the second tumour formed quite late in life at the age of 47." (PMID 40794298, 2025). "Possible risk factors for performance below average were higher complexity tumours (inner ear plus IAC/CPA), NF2, CI without tumour removal (“CI through tumour”), and sequential cochlear implantation after tumour removal (staged surgery)." (PMID 38992191, 2024). "High pPAK1 was observed in NF1-mutant, SUZ12-mutant ST88-14 MPNST cells independent of CRISPRi suppression of NF2, suggesting PAK1 activation may be conserved across de-differentiated Schwann cell tumors after loss of either tumor suppressors or epigenetic regulators." (PMID 38216572, 2024). "We found that the protein expression of NF1, TSC1, and TβRII, but not NF2 and PTEN was downregulated in metastatic nodules compared to the primary tumor tissues." (PMID 38997291, 2024). "A point mutant of TEAD converts NF2 into a potent suppressor of cGAS/STING signaling, strongly inhibiting cGAS/STING-mediated cell-autonomous and nonautonomous tumor immunity and suppressing nucleic acid recognition." (PMID 36497453, 2022). "Regarding B-cell infiltrates, which have been shown to play a role in promoting the anti-tumor immune response, interestingly, MPM tumors harboring LATS1/2 rather than NF2 display enriched plasma B-cell signature." (PMID 33805359, 2021). "The chronological order of the tumour-specific alterations, namely 22q LOH and somatic NF2 PVs, is probably not fixed and may be interchangeable." (PMID 40794298, 2025). "Although YAP/TAZ usually promote the expression of genes related to tumor promotion, early studies also showed that YAP/TAZ activation induced the transcription of their negative regulators, including LATS1/2, AMOT, and NF2, to establish a negative feedback loop and prevent tumorigenesis." (PMID 37211598, 2023). "Again, these data highlight differences between the published datasets GSE54934, GSE108524 and GSE141801 but suggest no clear difference between NF2-SWN and sporadic VS, with similar estimated abundances of cell types within the tumour predominantly composed of Schwann cells and macrophages." (PMID 37680691, 2023). "Mechanistically, this advantage was dependent on the RAC1P29S-mediated assembly of a dendritic actin network and lamellipodia formation, which sequestered and inactivated the tumour suppressor (and RAS inactivator) NF2/Merlin, independent of the focal adhesion and MAPK signalling." (PMID 35159327, 2022). "We previously reported that NF2 knockdown or forced YAP1 or TAZ expression in HOMC cell lines resulted in tumorigenicity in subcutaneously transplanted immunodeficient mice, while no tumor formation was detected when merely transplanting HOMC cell lines." (PMID 34663305, 2021).
cancer (240 papers, 2002 to 2026). A tumor composed of atypical neoplastic, often pleomorphic cells that invade other tissues. "Next, having established a quantifiable cancer-relevant phenotype robustly driven by NF2 loss, we tested spheroid growth in the presence of YAP/TAZ-TEAD inhibitors to quantify the impact of inhibition on the tumorigenic capacity of spheroids." (PMID 40744733, 2025). "Its inhibition has been shown to enhance ferroptosis by disrupting cell survival signaling, a mechanism particularly relevant in cancers harboring Ras or NF2 mutations." (PMID 40868287, 2025). "We have previously shown that the TCGA-defined YAP/TAZ signature gene set is up-regulated upon mesothelial NF2 loss specifically upon cancer-relevant stresses." (PMID 40744733, 2025). "We conducted a literature review on eleven different cancers with NF2 gene mutation involvement, summarizing the extent of association and specific biological pathways thought to be affected by NF2 mutations." (PMID 39796693, 2024). "Although these cancers have been extensively studied, NF2 mutations are rarer in these cancers and have thus been less frequently reviewed." (PMID 39796693, 2024). "Although NF2 gene mutations define several cancers, targeted immunotherapies for specific NF2 mutations are currently unavailable." (PMID 39796693, 2024). "The findings of this review provide insights into the role of NF2 mutations in cancers, Hippo signaling in NF2-mutant cancers, and current gaps in our knowledge regarding the two." (PMID 39796693, 2024). "The Hippo signaling pathway is a biological pathway that is involved in eight of the eleven NF2-mutated cancers studied in this review." (PMID 39796693, 2024). "Whole genome characterization and clonal evolution analysis confirmed neurofibromatosis 2 (NF2) gene loss as the main driver of this cancer." (PMID 39935847, 2024). "In terms of biological pathway involvement, 8 of the 11 cancers with NF2 mutations show evidence of Hippo signaling cascade involvement." (PMID 39796693, 2024). "In the present review, we found that 8 of the 11 cancers studied were described as having mutations in NF2 and had some degree of Hippo signaling pathway modulation." (PMID 39796693, 2024). "We synthesized studies across several oncologic fields to consolidate what we know about NF2 gene mutations in cancer development." (PMID 39796693, 2024). "Although NF2 mutations and their associated dysregulation of the Hippo pathway are characteristic of many cancers, it is important to discern NF2 mutants from a loss of NF2." (PMID 39796693, 2024). "The identification of an NF2 mutation through cancer gene panel testing provides valuable insights into potential therapeutic strategy." (PMID 38739347, 2024). "NF2 gene mutations have been identified in several cancers, many of which have implications in the Hippo signaling pathway." (PMID 39796693, 2024). "Of note were key biological pathways implicated in cancer formation resulting from sporadic NF2 mutations." (PMID 39796693, 2024). "We also explored the current understanding of how NF2 deficiency drives tumorigenesis from the perspective of cancer metabolism reprogramming and antitumour immunity." (PMID 38879686, 2024). "A loss of NF2 through chromosome 22 deletion similarly leads to the dysregulation of the Hippo signaling pathway, leading to cancer formation." (PMID 39796693, 2024). "Lastly, there were three cancers in this review that had studies describing NF2 mutations as simple associated mutations." (PMID 39796693, 2024). "Most importantly, the loss-of-function mutations of STK11 and NF2 are potential biomarkers of CVM-1118 which can be applied in the selection of cancer patients for CVM-1118 treatment." (PMID 37351538, 2023).
cancer (continued). "To investigate this, we utilised the Cistrome Data Browser102 to visualise the binding of TEAD members to genes dysregulated on NF2 loss in cells across a wide range of widely‐used cancer cell lines, including MSTO‐211H, a cell line derived from PM tissue." (PMID 36740402, 2023). "PRCC also displays mutations in previously studied cancer-related pathways; these include NF2 (Hippo pathway), SMARCB1 and PBRM1 (SWI/SNF complex), and chromatin modifier pathways (SETD2, KDM6A, and BAP1)." (PMID 38162463, 2023). "Mutation of NF2 (the Hippo pathway tumor suppressor) was observed in a number of PRCCs, and this pathway has been targeted in other cancers." (PMID 36927438, 2023). "The E-cadherin-Merlin-Hippo-YAP axis is frequently mutated in cancer, and malignant alterations of multiple members in this signaling axis all makes cancer cells sensitive to ferroptosis, and Merlin (NF2) is an important member of this axis." (PMID 35847022, 2022). "Four of the five NF2 mutations present were approximately clonal (cancer cell fraction >0.75), while two out of three FAT1, PTPRT, and EP300 mutations each were approximately clonal." (PMID 35288096, 2022). "Further investigations will be required to examine if JM7 is effective in other cancers with NF2 mutation." (PMID 36523977, 2022). "Another cancer-associated mutation that alters signaling pathways occurs in the tumor suppressor NF2 (Neurofibromin 2)." (PMID 35406602, 2022). "The spontaneous malignant transformation was characterized by a near-total whole-genome doubling, disappearance of NF2 mutation and new mutations in three cancer-related genes (GNAQ, FOXO4 and PDGFRB)." (PMID 34816314, 2022). "Bioluminescence imaging showed multiple metastases in mice administered shNF2-GPX4-iKO cells, while no metastases were found in those administered shNT-GPX4-iKO cells, suggesting that NF2 deficiency stimulates cancer metastasis." (PMID 35847022, 2022). "Only three mutations were in genes linked to cancer development: NF2 I174fs and MLL3 both detected in the LR-Om and characterized as pathogenic, and WT1 in the KR lesion." (PMID 34301805, 2021). "Studies of mouse and tumor patients showed that the inactivation of NF2 is an important cause of cancer." (PMID 34150758, 2021). "This indicates that gene mutation and gene deletion are both common means of NF2 loss of function in human cancers." (PMID 34150758, 2021). "Due to involvement of multiple pathways in NF2 associated lesions as well as in malignant tumors, MEKi are also used in combination therapies." (PMID 33863389, 2021). "Somatic loss-of-function NF2 mutations are also found in many other kinds of cancers such as mesotheliomas and bladder, thyroid, and skin cancer." (PMID 34150758, 2021). "While homozygous deletion of Nf2 in murine embryos causes embryonic lethality, Merlin loss in adult tissue is implicated in Neurofibromatosis type 2 disorder and cancer." (PMID 32299434, 2020). "For example, deficiency or inactivation of NF2, which functions to initiate and orchestrate the Hippo pathway, has been reported to be a frequent tumorigenic event in several cancer types." (PMID 33489905, 2020). "Inhibition of the core Hippo pathway components via point mutations and epigenetic alterations are found in subsets of human cancers including mutations in NF2, MST1/2, SAV1, MOB1A/B, LATS1, and LATS2." (PMID 31212916, 2019). "Strikingly, while our work was under review, a new study directly linked cancer cell ferroptosis to NF2-YAP signalling." (PMID 31568497, 2019). "Since PAK1 inhibitors has been suggested as putative candidate for NF2 deficient cancers including NF2 syndrome, IPP-14 would be one of plausible chemicals for NF2 syndrome and other cancers." (PMID 28423593, 2017).
cancer (continued). "For example, merlin/NF2 is a complex gene that is involved in a number of signalling pathways including Src/Fak, Hippo, Ras/Rac/PAK, ERK1/2, AKT and CRL4-DCAF, with somatic NF2 mutations occurring in various cancers." (PMID 27438856, 2016). "It has been shown that NF2 function or expression is lost in various cancers through mutation or chromosome deletion." (PMID 26980710, 2016). "Novel targeted therapies are now being used in a small number of cases to treat hereditary neurofibromatosis 2 and cancers harboring NF2 mutations." (PMID 24393766, 2014). "Data collected from COSMIC and ICGC databases and published studies show that diverse cancers harbor somatic NF2 mutations." (PMID 24393766, 2014). "Thus, our results indicate that de novo pyrimidine biosynthesis is a cancer-dependent process in NF2-deficient PM." (PMID 40707702, 2025). "Furthermore, the detection of PMS individuals harboring ring chromosome 22 is essential, as these individuals have an increased risk of cancer, due to possible loss of the NF2 gene (2–4%)." (PMID 40102980, 2025). "Suppressing MAPK1, a mutated variant of the NF2-Ras signaling pathway, may increase the sensitivity of cancer cells to ferroptosis, which can eventually lead to targeted cell death in therapy-resistant cancers." (PMID 40868287, 2025). "However, interestingly, in the same cancer clone as NF2, we identified a potential BRCA2 driver mutation (p.E51K) present in all tumors along with a SETD2 (p.S1885N) mutation present only in the recurrence." (PMID 39935847, 2024). "Therefore, in this review, we summarize the cross-cancer mutation patterns and subsequent biological alterations in NF2-related tumors." (PMID 38879686, 2024). "Through analyses of the cancer genome, the Neurofibromatosis 2 (NF2) gene has been identified as one such gene that, when mutated, acts as a driver of mutations with the potential to promote the carcinogenesis of several cancers." (PMID 39796693, 2024). "Clonal evolution analysis confirmed NF2 gene loss as the main driver of this cancer." (PMID 39935847, 2024). "The ability to block YAP/TAZ function has been of interest in treating NF2-deficient cancers." (PMID 38336988, 2024). "In the same cancer clone as NF2, we identified a BRCA2 (p.E51K) mutation was present in all tumors, which may represent a potential driver event, though evidence supporting this is currently limited." (PMID 39935847, 2024). "Genetics also defines a prominent role of NF2 loss of function in cancer." (PMID 37280085, 2023). "This suggests CVM-1118 may have the potential to treat cancer patients carrying STK11- or NF2-deficient mutation–via targeting TRAP1 and inhibiting the activation of mTOR/AKT signaling pathways." (PMID 37351538, 2023). "It is inferred that neoantigens produced by NF2/YAP mutated cancer cells can be identified by serological analysis techniques of recombinant expression cDNA clones, total exon sequencing (WES) combined with RNA sequencing (RNA-seq) and epitope prediction methods, and LC-MS/MS methods." (PMID 34123855, 2021). "In addition, molecules related to the NF2/YAP(neurofibromin 2/Yes-associated protein 1) signaling pathway, which are often malignant mutations in cancer, have also been found to play an important role in the regulation of ferroptosis." (PMID 34123855, 2021).
cancer (continued). "A recent study demonstrated that intercellular interaction between epithelial cells medicated by E-cadherin could suppress ferroptosis through Merlin-YAP signaling and inactivation of NF2, the Merin-encoding gene, enabled cancer cells to cause ferroptosis." (PMID 33727924, 2021). "Somatic NF2 mutations have been reported ina number of different cancers (Schroeder etal., 2014)." (PMID 31188922, 2019). "Whereas NF1 and NF2 guarantee the formation of especially multiple benign tumors (including non-diffuse gliomas) in a lifetime, Li–Fraumeni patients pose a greater risk to developing a malignant tumor, including a diffuse glioma." (PMID 29616301, 2018). "Thus, selective PAK1 inhibitor has been proposed to be potent candidate target for NF2 syndrome as well as NF2 deficient human cancers such as mesothelioma." (PMID 28423593, 2017). "Thus, this chemical would be one of strong candidate for anti-cancer drug against various human malignancies including pancreatic cancers, colon cancer as well as NF2 deficient cancers." (PMID 28423593, 2017). "Chemical inhibitors of the STRIPAK complex are expected to activate MST1/2 and downstream signaling, and may have therapeutic potential in treating human cancers driven by NF2 mutations or elevated expression of YAP/TAZ." (PMID 29063833, 2017). "Finally, we tested the effect of IPP-14 on NF2-deficient cancer cell lines, because NF2 suggested as PAK1 inhibitor." (PMID 28423593, 2017). "Based on these premises, we used MDP to seek for compounds that could specifically target cancer cells bearing NF2 gene mutations and thus with aberrant YAP/TAZ activity." (PMID 26513174, 2015). "This region has multiple missense mutations in both cancer and NF2." (PMID 24393766, 2014). "Mutations in the NF2 gene, which encodes Merlin have been reported in a number of cancers including approximately 30% of melanomas and could have an important role in the efficacy of the Hippo pathway." (PMID 23720711, 2013). "With the exception of a few hereditary susceptibility genes, such as NF1 and NF2, drivers for this cancer type remain largely unknown." (PMID 24009526, 2013). "Next, in order to better understand which, if any, driver mutations besides NF2 may be associated with cancer initiation, progression, and metastases, we used Cancer Genome Interpreter (CGI) to assign known or predicted novel driver status to nonsynonymous mutations." (PMID 39935847, 2024). "The mechanism by which NF2 mutations drive cancer is unknown but recent results show that mutation in the FERM domain of NF2 lead to a gain-of-function ability to form biomolecular condensates that sequester and inactivate IRF3 and TBK1, disrupting the cGAS-Sting pathway." (PMID 35406602, 2022). "Therefore, malignant mutation events in molecules involved in the NF2/YAP signaling pathway could predict the sensitivity of cancer cells to iron-induced death therapy." (PMID 34123855, 2021). "Therefore, endpoints of trials for NF2 associated tumors differ compared to other cancer studies." (PMID 33863389, 2021). "Although the mechanisms by which merlin suppresses mTOR signaling remain elusive, NF2 inactivation has been found to confer sensitivity to rapalogs in bladder cancer, suggesting that mTORC1 signaling likely sustains the expansion of merlin-deficient cancer cells." (PMID 29565815, 2018). "Thus, understanding the neurofibromin 2 activation mechanism will increase our knowledge of the role of NF2 mutations in cancer and might eventually aid prognosis and future chemotherapeutic therapies." (PMID 29626191, 2018). "Heterozygous and homozygous deletion of YAP dramatically suppresses tumorigenesis in LKB1-, Mob1-, and NF2-deficient liver, Mst1/2-deficient phenotypes in the small intestine and colon, and the early progression to pancreatic ductal adenocarcinoma in a Kras (G12D) cancer model." (PMID 28035075, 2017).